GAS6 (growth arrest specific 6)
Diseases named in the same sentence as GAS6 in open-access papers (continued):
Sharing a sentence is not in itself a finding about the gene and the disease.
breast carcinoma (continued). "Increased Gas6 expression correlating with favorable prognosis has so far only been reported in human breast cancer and in RCC, which partly may be explained by mechanisms presented here." (PMID 19888345, 2009). "Recently, Gas6 has been shown to be a target for overexpression and amplification in breast cancer." (PMID 18283315, 2008). "Moreover, the Gas6 locus has recently been described as a target for amplification in mouse models of breast cancer and in human breast cancer." (PMID 18283315, 2008). "Gas6 is an attractive target for molecular manipulation, as it is the ligand of the Axl tyrosine kinase receptor, which has previously been shown to be overexpressed in a subset of breast carcinomas." (PMID 18283315, 2008). "In “Gene Expression Predicts Dormant Metastatic Breast Cancer Cell Phenotype,” the authors find genes (Cfh, Gas6, Mme, Ogn) that are significantly expressed in dormant cells within bone (in mice), which correspond with disease-free survival in original tumors of human breast cancer." (PMID 41465319, 2025). "To determine whether Gas6 is preferentially expressed in a particular breast cancer subtype, we categorized patient samples from the TMAs as luminal A, luminal B, Her2+ and TNBC, based on clinical attributes including hormone receptor status, Her2 status, and Ki67 expression." (PMID 32352034, 2020). "Our previous studies have shown that the Se/FO combination treatment increases the therapeutic efficacy of anti-cancer agents against breast cancer via the dose-dependent downregulation of TGF-β/TβR-2, AXL/Gas6, and β-catenin signaling." (PMID 36547898, 2022). "The AXL/Gas6 pathway is a potent EMT inducer and a metastatic phenotype promoter, that has been proposed as a pharmacological target in breast cancer for its role in controlling the invasive phenotype of cancer cells." (PMID 34452195, 2021). "Another means by which AXL can promote invasion is through GAS6-mediated phosphorylation of the Elmo scaffold proteins by AXL to ultimately activate Rac GTPase, which also promotes breast cancer cell proliferation." (PMID 32148495, 2020). "In breast cancer, AXL’s activation, mediated by the link with GAS6, has been deeply studied, especially for its role in the connections between the tumor microenvironment (TME) and cancer cells." (PMID 33182542, 2020). "In HER2-amplified breast cancer, AXL heterodimerization with HER2 allows its GAS6-independent activation and promotes drug resistance and tumor progression." (PMID 33182542, 2020). "In breast cancer cells, DN10764 was found to inhibit cell proliferation and GAS6-mediated AXL signaling pathways, resulting in the suppression of migration and invasion." (PMID 27829217, 2016). "In breast cancer cells, DN10764 inhibited cell proliferation and GAS6-mediated AXL signaling, consequently resulting in suppressed migration and invasion." (PMID 27829217, 2016). "Indeed, Cfh, Gas6 and Ogn expression correlated with better relapse-free survival (RFS) among breast cancer patients across several datasets." (PMID 35093137, 2022). "Although the present study did not examine the role of Gas6 on prostate and breast cancer cells, we predict that Gas6 is an important ligand that mediates autocrine and paracrine signaling axes between neoplastic and stromal cells." (PMID 33791875, 2021). "In addition to the PI3K/Akt cascade, GAS6-induced AXL activation and triggers kinase signaling, including ERK and PEAK1, which contribute to the high invasiveness of breast cancer cells." (PMID 34831142, 2021). "In addition to ProS1, Gas6 was also found to be strongly expressed in particular cancer cell types, with the highest levels in MDA-MB-231 breast cancer cells." (PMID 31766614, 2019).
breast carcinoma (continued). "Breast cancer cells with overexpression of Axl have mesenchymal cellular phenotype; it does not rely on the existence of Axl's ligand Gas6." (PMID 31281396, 2019). "However, knockdown or overexpression of each of these genes (Cfh, Gas6, Mme, Ogn) individually in breast cancer cells had no measurable impact on tumour burden when implanted into mice, although dormant cell numbers were not reported in this study." (PMID 41091336, 2025). "Conversely, clinical studies have shown a correlation between GAS6 expression and patients’ survival in breast cancer, suggesting that GAS6 may not be essential in this context." (PMID 35158733, 2022). "These tumor features do not correspond to the ones found in Amp13q34 tumors, which are mainly ER and PR negative; thus, GAS6 may not be the target gene in the Amp13q34, but may still play a role in other breast cancers." (PMID 19995430, 2009). "Furthermore, as Gas6 mRNA expression may not predict breast cancer outcomes, the assessment of Gas6 protein expression or serum levels, as a potential biomarker for patient response and outcome, is also warranted." (PMID 34576116, 2021). "In the present study, our data showed that stromal Gas6 expression did not significantly change during breast cancer progression, however it remains unclear as to whether macrophage-derived Gas6, or Gas6 from other stromal cells, has tumor-promoting activities." (PMID 32352034, 2020). "However, the expression and relevance of Gas6 in human breast cancer patients has not been studied." (PMID 32352034, 2020). "In breast cancer, the role of miR-126 in tumor metastasis may be related to the negative regulation of insulin receptor substrate-1 expression and it inhibits endothelial cell recruitment and angiogenesis through the negative regulation of IGFBP2/IGF1/IGF1R and GAS6/ MERTK signaling pathways." (PMID 24350576, 2013). "This clinical observation, therefore, highlighted the non-exclusive correlation between GAS6 and AXL in breast cancer progression." (PMID 33182542, 2020). "Thus, it is plausible that Axl-mediated breast cancer progression may not require Gas6." (PMID 32352034, 2020).
lung cancer (34 papers, 2013 to 2026). A malignant neoplasm involving the lung. "It was observed that Gas6 is frequently overexpressed in lung cancer cells and is found in the plasma, and Gas6 is associated with cell growth of stromal cancerous cells and tumor progression." (PMID 35053080, 2022). "Although Gas6 regulates inflammatory functions in immune and endothelial cells, in lung cancer cell-associated venous thrombosis model, Gas6 enhanced prostaglandin E2 (PGE2) secretion from the endothelium leading to platelet activation and venous thrombosis." (PMID 34322381, 2021). "Cancer-associated fibroblasts can also produce Gas6 following therapy leading to the migration of AXL-positive lung cancer cells." (PMID 31963783, 2020). "Recombinant GAS6 promotes lung cancer cell migration, and its expression in the tumor stroma is correlated with poor clinical outcomes." (PMID 40940956, 2025). "GAS6, secreted by CAFs, facilitates the migration of Axl-expressing lung cancer cells during chemotherapy." (PMID 40940956, 2025). "Drawing from reports indicating that the up-regulation of AXL kinase and its ligand GAS6 can confer resistance to EGFR-targeted therapy in lung cancer, we investigated the expression levels of these genes in both lung and melanoma persister cells." (PMID 38473364, 2024). "In this study, we found that AXL and its ligand GAS6 were highly expressed in many malignant tumors not only in lung cancer." (PMID 35782741, 2022). "In recent years, the involvement of the VKDPs in lung cancer has become intensely studied, with recent studies reporting especially the role in tumor progression of Gas6 and MGP." (PMID 35053080, 2022). "Increased expression of Axl and its ligand Gas6 was found in EGFR-mutant lung cancers obtained from individuals with acquired resistance to erlotinib." (PMID 36059952, 2022). "Recent studies report that the blockade of TGF-β/TβR, Wnt/β-catenin, and AXL/Gas6 signaling can potentially reduce the EGFR-TKI resistance in lung cancer A549, HCC827, and PC9 cell lines." (PMID 36547898, 2022). "Analysis of mouse lung tumors revealed MerTK staining on tumor cells and in vitro studies showed that Gas6 increased proliferation of human lung cancer cell lines." (PMID 31903163, 2019). "Active MerTK was found in human lung cancer cell lines in culture and addition of Gas6 induced proliferation of these cells." (PMID 31903163, 2019). "Blocking Gas6 protein production via warfarin treatment reduced lung tumorigenesis in two different lung cancer models, urethane and LSL-K-RasG12D." (PMID 31903163, 2019). "We found that lung macrophages are the primary source of Gas6 in lung cancer models and its production is inversely regulated by the NF-κB pathway." (PMID 31903163, 2019). "The RTK AXL which binds to a secreted ligand Gas6 has been shown to be a rigidity sensor and facilitate a decrease in cellular stiffness in lung cancer." (PMID 31172946, 2019). "Together, these studies indicate that the Gas6-MerTK pathway limits the effectiveness of NF-κB inhibition in lung cancer development and progression, thus supporting wider use of combined targeted therapies for lung cancer." (PMID 31903163, 2019). "In the present study, we analyzed Gas6 expression in CAFs and its alteration by chemotherapy using a mouse model and cells derived from human lung cancers; we also examined the effects of Gas6 secreted by CAFs on lung cancer cells." (PMID 28878389, 2017). "We have demonstrated that one pathway by which an altered tumor stromal microenvironment following chemotherapy promotes malignancy of lung cancer cells is through the Gas6–Axl axis." (PMID 28878389, 2017). "To elucidate the biological significance of AXL in lung cancer metastases, especially in NSCLC with brain metastases, we tested the expression of AXL and its ligand GAS6 in the selected 98 lung cancer specimens by immunohistochemical staining." (PMID 28551766, 2017).
lung cancer (continued). "Based on these findings, it is presumed that Gas6 derived from CAFs promotes migration of Axl-expressing lung cancer cells during chemotherapy and is involved in poor clinical outcome." (PMID 28878389, 2017). "In this study, we demonstrated that Gas6 expression by CAFs increases during chemotherapy and that its secretion by CAFs promotes proliferation and migration of lung cancer cells." (PMID 28878389, 2017). "Furthermore, RU-301 and RU-302 disrupted GAS6-inducible TAM activation, inhibited GAS6-inducible cell motility in lung cancer and triple-negative breast cancer cell lines, and suppressed lung cancer growth in a mouse xenograft model." (PMID 39062902, 2024). "We, therefore, used the A549 lung cancer cell line, which is often used to study Gas6 signaling." (PMID 38137053, 2023). "Gas6, derived from CAFs (carcinoma-associated fibroblasts), may promote the migration of AXL-expressing lung cancer cells during chemotherapy." (PMID 35053080, 2022). "In addition, we assessed Gas6 expression by bone marrow-derived macrophages from WT and IKKβΔMye mice after incubation with culture media from lung cancer (Lewis Lung Carcinoma, LLC) cells." (PMID 31903163, 2019). "To investigate whether Gas6 plays a role in resistance to NF-κB inhibitors, which have not proven to be effective agents for lung cancer therapy, we studied lung cancer models induced by urethane injection or expression of mutant Kras (KrasG12D)." (PMID 31903163, 2019). "The Gas6−/− mice formed much smaller thrombi than their WT counterparts, however larger thrombi were seen in Gas6−/− mice by injecting recombinant GAS6, indicating GAS6 inhibition may have anti-thrombotic effects in the setting of lung cancer." (PMID 29868590, 2018). "In the present study, we demonstrated the presence of Gas6 in CAFs isolated from human lung cancer." (PMID 28878389, 2017). "Moreover, the co-expression relationship between AXL and GAS6 was further confirmed by IHC assays in serial sections of lung cancer metastasis tissues." (PMID 28551766, 2017). "Also, we showed that inhibiting the canonical NF-κB pathway in macrophages up-regulates Gas6 expression, thereby unmasking an important, pro-tumorigenic role for this pathway in lung cancer that appears to be mediated through increased tumor cell proliferation." (PMID 31903163, 2019). "AXL/GAS6 are known to be a pivotal signaling axis involved in EMT, which could conceivably be the underlying factor in leading to tumor progression and adverse prognosis in lung cancer BM." (PMID 28551766, 2017). "Here we demonstrated that BrM-CSCs mimic the pericytes by overexpressing CD146 in the brain TME, which is induced by the reactive astrocyte-derived GAS6, and exerts a potent pro-angiogenesis effect by dual effects on the VEGFA/VEGFR axis in lung cancer BrM." (PMID 41356185, 2026). "Considering the role of these three molecules in lung cancer pathology, the main goal of this study was to assess their serum concentration before and after treatment and investigate how MGP, Gas6, EGFR, and VK1 are modified after one cycle of chemotherapy." (PMID 35053080, 2022). "LC‐MS/MS proteomic analysis reveals that CAFs that overexpress hMENAΔv6 secrete the AXL ligand GAS6, favoring the invasiveness of AXL‐expressing pancreatic ductal adenocarcinoma (PDAC) and non‐small cell lung cancer (NSCLC) cells." (PMID 32909687, 2020). "However, whether CAFs in human lung cancers could be a source of Gas6 remains unclear." (PMID 28878389, 2017). "In the subgroup of lung cancer with metastases to organs other than brain, high AXL and GAS6 expression accounted for nine of 32 (28.1%) in both markers." (PMID 28551766, 2017). "Many of the Gas6/AXL studies have concentrated on lung cancer, but not much is known about other different environments where Gas6 and AXL are affected as those observed during PE." (PMID 35741013, 2022).
lung cancer (continued). "Despite the inherent resistance to global NF-κB inhibition, targeted combination therapies, like NF-κB and Gas6/TAMR inhibition, could be effective for treatment of lung cancer." (PMID 31903163, 2019). "For example, EGFR-TKI resistance could be caused by MET amplification, HGF-triggered MET activation, Gas6-triggered AXL activation, and HER2 amplification in EGFR mutant lung cancer." (PMID 24952482, 2014). "Although some reports have already mentioned the expression or effects of Axl in lung cancer, specific or detailed clinical impact of both Axl and Gas6 expression have not, thus far, been fully investigated." (PMID 23242819, 2013).
ovarian carcinoma (29 papers, 2008 to 2025). A malignant neoplasm originating from the surface ovarian epithelium. "AXL and/or GAS6 overexpression have been reported in multiple human cancers such as glioma, melanoma, breast, lung, and ovarian cancer, and high level of AXL was associated with increased tumor progression and poorer overall survival." (PMID 35622156, 2022). "The authors observed that GAS6 and its encoded protein were overexpressed in ovarian cancers; however, the relationship between GAS6 expression in levels and various clinicopathological parameters was not reported." (PMID 23878800, 2013). "Silencing AXL or blocking the GAS6-AXL pathway has been shown to prevent regional dissemination of ovarian cancer cells in vivo, demonstrating AXL to be a critical factor in ovarian tumour metastasis." (PMID 40696160, 2025). "Blocking GAS6/AXL signaling was also reported to increase DNA damage to sensitize ovarian cancer to chemotherapy and PARP inhibition." (PMID 38906855, 2024). "Among the genes that were highly expressed and commonly significant LR pairs in both the R and NR groups, CD74, GAS6, and VEGFA were associated with carcinogenesis and were prominent markers of targeted therapy in ovarian cancer." (PMID 39135097, 2024). "Growth arrest specific 6 (Gas6) binds to Axl, a receptor tyrosine kinase which is specifically expressed on ovarian cancer cells over normal cells." (PMID 39135999, 2024). "It was shown that Gas6 is expressed in many tumor types, such as pancreatic and ovarian cancer, melanoma, and leukemia." (PMID 35760058, 2022). "Gas6/Axl expression was higher in patients with residual ovarian cancer or in metastatic ccRCC patients." (PMID 35760058, 2022). "Specifically, Gas6 is overexpressed in melanoma, schwannoma, glioma and pancreatic ductal adenocarcinoma (PDA) cell lines, and several studies have shown that Gas6 is upregulated in ovarian cancer and thyroid cancer specimens from patients." (PMID 29386018, 2018). "Altogether, these data suggest that Gas6/Axl signaling leads to PI3K/AKT/rac activation in ECM-adherent ovarian cancer cells in a src-independent way." (PMID 26356564, 2015). "In order to assess the biochemical and cellular mechanisms activated in ovarian cancer cells by Gas6, SKOV3 cells were Gas6 stimulated while adhering to FN, and the actin assembly was evaluated by immunofluorescence (IF) with labeled phalloidin." (PMID 26356564, 2015). "To clinically validate the results obtained in vitro in established ovarian cancer cell lines, we first assessed the presence of Gas6 in 22 HGEOC ascites, whose characteristics have been described elsewhere." (PMID 26356564, 2015). "We first checked by real time RT-PCR the expression of Gas6 and Axl, Mer, and Tyro-3 in a panel of human ovarian cancer cell lines." (PMID 26356564, 2015). "Hereby, GAS6 is roughly in the middle of this top candidate group, where also well-known ovarian cancer markers like HE4 (WFDC2) or DDR1 are listed." (PMID 23878800, 2013). "We performed immunohistochemistry on various ovarian cancer tissues and found that GAS6 expression was elevated in tumour tissue samples compared to healthy control samples (P < 0.0001)." (PMID 23878800, 2013). "With our meta-analysis of transcriptomic data revealing that GAS6 mRNA is highly expressed in ovarian cancer, we assessed the expression of GAS6 in various ovarian tissues by immunohistochemistry." (PMID 23878800, 2013). "This analysis revealed that GAS6 was highly expressed in ovarian cancer and therefore was selected as our candidate of choice." (PMID 23878800, 2013). "Our data propose GAS6 as an independent predictor of poor survival, suggesting GAS6, both on the mRNA and on the protein level, as a potential biomarker for ovarian cancer." (PMID 23878800, 2013). "AXL is often expressed together with GAS6 in a variety of human cancers, often being highly expressed in advanced stage human breast and ovarian cancer." (PMID 22570691, 2012).